VSX1 (visual system homeobox 1)
Diseases named in the same sentence as VSX1 in open-access papers (continued):
Sharing a sentence is not in itself a finding about the gene and the disease.
keratoconus (continued). "The role of VSX1 variations in a minority of keratoconus patients may be influenced by its possible variable penetrance or pleiotropic effect in corneal tissue." (PMID 23506487, 2013). "The role of VSX1 in the pathogenesis of keratoconus has also been controversial." (PMID 23592923, 2013). "The involvement of VSX1 gene for the genetic basis of keratoconus is unclear and controversial." (PMID 23506487, 2013). "The lack of VSX1 pathogenic variations in a large number of unrelated sporadic keratoconus patients tend to omit its role, and corroborate the involvement of other genetic, environmental or behavioural factors in the development of this complex disorder." (PMID 23506487, 2013). "This study examines whether VSX1 plays a role in the pathogenesis of keratoconus and PPCD in a New Zealand population." (PMID 23592923, 2013). "In this pilot study we reported the results of mitochondrial complex I gene analysis in 20 keratoconus patients negative for Visual System Homeobox 1 (VSX1) mutations." (PMID 21691575, 2011). "Other studies did not report VSX1 mutations in diverse population cohorts of keratoconus patients, including Saudi keratoconus patients." (PMID 21528002, 2011). "In this study, we performed linkage analysis for six known chromosomal loci as well as a mutation detection screen in VSX1 and SOD1 in 112 affected, 52 unaffected family members and 100 normal individuals as controls in a group of Iranian patients with keratoconus." (PMID 22171159, 2011). "VSX1 may have an important role in the pathogenesis of keratoconus which needs further investigation." (PMID 21365019, 2011). "This is not the case for the visual system homeobox 1 (VSX1) gene where mutations associated with keratoconus cases have been found in different studies." (PMID 21528002, 2011). "Twenty Saudi Arabian patients with isolated keratoconus, no family history of the disease and no mutations in VSX1 were recruited." (PMID 21528002, 2011). "VSX1 sequence changes observed in keratoconus patients and controls." (PMID 21403853, 2011). "The lack of pathogenic sequence changes in VSX1 in our keratoconus cohort, indicates that VSX1 mutations are not responsible for keratoconus cases in this population." (PMID 21403853, 2011). "In this study we analyzed mitochondrial complex 1 gene in 20 keratoconus patients (negative for VSX1 mutations) and 20 unrelated healthy controls." (PMID 21691575, 2011). "This indicates that keratoconus is a complex condition of multi-factorial etiology and that mutations in VSX1 are not responsible for all cases of keratoconus." (PMID 21403853, 2011). "The mother who also had the same change but did not have VKC did not develop keratoconus.The sister who had VKC but did not have mutation in VSX1 did not manifest the disease." (PMID 21365019, 2011). "Mutational analysis of VSX1, SPARC, and SOD1 in 302 subjects affected by keratoconus." (PMID 21976959, 2011). "In these latter cases, the VSX1 changes found in keratoconus patients and in their normal relatives could represent genetic predisposition factors (a defect in one of the multiple factors needed to manifest the pathological phenotype)." (PMID 21976959, 2011). "Although our findings support VSX1 as a plausible candidate gene responsible for keratoconus, other chromosomal loci and genes could be involved in KTCN development." (PMID 22171159, 2011). "In this study we analyzed VSX1 in 50 unrelated keratoconus patients and controls from north India." (PMID 21139977, 2010). "In fact, VSX1 may have a pleiotropic action among the tissues of the cornea leading to keratoconus in some cases as observed for the transforming growth factor (TGFBI) gene; which causes four distinct autosomal dominant corneal diseases." (PMID 21139977, 2010). "The role of VSX1 in the pathogenesis of keratoconus is still controversial." (PMID 21139977, 2010).
keratoconus (continued). "Several genetic variants of the VSX1 gene have been reported from various parts of the world but a definite pathogenic role of the genetic variants in causation of keratoconus is not yet established." (PMID 19956409, 2009). "Also, VSX1, SOD1, and LOX genes are associated with keratoconus in some studies." (PMID 40002778, 2025). "Several variants of the VSX1 gene have been reported from various parts of the world, but a definitive pathogenic role of these variants in keratoconus has not yet been established because segregation of these variants was also seen in some unaffected individuals." (PMID 28950846, 2017). "VSX1 (Visual system homeobox 1), TIMP3, TGFBI, ZEB1, filaggrin (FLG) and several collagen genes, such as COL4A3, COL4A4 AND COL5A1, have been associated with keratoconus, while the distinct potential loci, which have been described, include 3p14-q13, 5q21, 5q32 and 14q11." (PMID 28932340, 2017). "As the greatest percentage of our patients with keratoconus were of a unique Polynesian ethnicity, this may suggest that VSX1 does not play a causative role within this ethnic group." (PMID 23592923, 2013). "In our keratoconus cohort, no pathogenic VSX1 mutation(s) were identified." (PMID 21403853, 2011). "So lack of possibly pathogenic changes in VSX1 gene in keratoconus patients suggests that mutations of VSX1 could only be responsible for a very small fraction of all observed cases and need to be investigated in different populations." (PMID 21139977, 2010). "Taken together, the VSX1 gene may contribute in a very small number of cases with clear segregation in families identified, however, rare potentially pathogenic variants in this gene do not contribute widely to keratoconus susceptibility in our cohort." (PMID 29924831, 2018). "This study investigated VSX1 changes in all seven exons in a population with PPCD and keratoconus, with a significant Polynesian ethnic proportion." (PMID 23592923, 2013). "In contrast, the genes VSX1 and SOD1, were initially proposed to play a role in keratoconus due to the identification of sequence variants in keratoconus patients that were absent in controls." (PMID 29924831, 2018). "Although different studies have found sequence variants of the visual system homeobox 1 (VSX1) gene associated with keratoconus in humans, no research has detected such variants in sporadic keratoconus patients from China." (PMID 28950846, 2017). "Molecular analysis identified the VSX1 mutation Q175H in the affected brother and in the mother who had neither VKC nor keratoconus but only the VSX1 Q175H sequence change." (PMID 21365019, 2011). "In contrast, other studies examining sporadic or familial keratoconus and PPCD1 have failed to reveal VSX1 mutations." (PMID 21437200, 2011). "To date, VSX1 is recognized as a possible but not definitive KC gene—some mutations in VSX1 may cause atypical corneal dystrophies (like posterior polymorphous corneal dystrophy) that can co-occur with keratoconus, but the majority of sporadic KC cases do not seem to be explained by VSX1 mutations." (PMID 41595486, 2026).
posterior polymorphous corneal dystrophy (14 papers, 2008 to 2026). Posterior polymorphous corneal dystrophy (PPCD) is a rare mild subtype of posterior corneal dystrophy characterized by small aggregates of apparent vesicles bordered by a gray haze at the level of Descemet membrane, generally with no effect on vision. "VSX1 is essential for craniofacial and ocular development, and it has been reported that VSX1 mutations play a pathogenic role in posterior polymorphous corneal dystrophy." (PMID 36463181, 2022). "H244R mutation of VSX1 was reported to be associated with selective cone ON bipolar cell dysfunction and macular degeneration in a family with posterior polymorphous corneal dystrophy." (PMID 32111086, 2020). "Nevertheless, VSX1 mutations have been identified in two different corneal phenotypes - posterior polymorphous corneal dystrophy (PPCD) and KC." (PMID 25963163, 2015). "The exclusion of VSX1 is particularly interesting as mutations in this gene have been associated with some cases of posterior polymorphous dystrophy (PPMD), a condition that can be confused with primary juvenile open-angle glaucoma." (PMID 18648523, 2008). "VSX1 is crucial for the development of the craniofacial structures and eyes, and studies have indicated that mutations in VSX1 contribute to the pathogenesis of posterior polymorphous corneal dystrophy." (PMID 40558291, 2025). "VSX1 mutations are also associated with posterior polymorphous dystrophy." (PMID 21403853, 2011).
corneal dystrophies (6 papers, 2011 to 2026). "This has led to the suggestion that VSX1 functions as a corneal damage response gene and that corneal dystrophies associated with changes in VSX1 are linked to defects in the corneal wound-healing pathway." (PMID 21437200, 2011). "Our PPI network analysis also revealed interactions between ZNF469 and CCT candidate genes, including COL5A1, COL1A1, and other genes that regulate eyeball development, such as VSX1 (causing KC and corneal dystrophy) and CHST14 (Ehlers-Danlos Syndrome candidate gene)." (PMID 40547359, 2025). "Future experiments examining the pathogenicity of VSX1 mutations associated with corneal dystrophy are required to rule out species differences and possible non-cell autonomous roles for VSX1 in the cornea." (PMID 21437200, 2011). "The VSX1 (visual system homeobox 1) gene belongs to a family of homeodomain transcription factors that are thought to control cell differentiation in craniofacial and ocular development, making it a promising functional candidate gene for KC pathogenesis of various corneal dystrophies." (PMID 27350955, 2016).
clear cell renal cell carcinoma (4 papers, 2022 to 2025). "High VSX1 expression promotes the aggressiveness of clear cell renal cell carcinoma through transcriptional regulation of FKBP10." (PMID 39023752, 2024). "Therefore, investigating whether VSX1 influences the progression of renal clear cell carcinoma through downstream TMEM44 warrants further investigation." (PMID 37561335, 2024). "Additionally, overexpression of VSX1 has been shown to increase the activity of TMEM44, FKBP10, and TRIB3, and enhance the growth of renal clear cell carcinoma." (PMID 37561335, 2024).
corneal disease (3 papers, 2011 to 2023). "This study aimed to resolve the question of corneal Vsx1 expression in mice and evaluate a possible explanation for the association of VSX1 mutations with corneal disease." (PMID 21437200, 2011). "Despite the well characterized role for Vsx1 in mouse retinal bipolar cells, the role of VSX1/Vsx1 in human corneal disease is controversial." (PMID 21437200, 2011).
diabetes (2 papers, 2015 to 2018). "TCF3 is highly expressed in islets of T2D patients and is associated with Wnt signaling in diabetes pathogenesis; and VSX1, expressed in ocular tissues, is associated with eye diseases." (PMID 25898945, 2015). "Therefore, our findings and existing published evidences can lead to the hypothesis that mutations in the CNTN4 gene modify its binding with TCF3 in the pancreas and VSX1 in the brain and activate related genetic regulations for diabetes and its complications." (PMID 25898945, 2015).
microphthalmia (2 papers, 2023 to 2024). Congenital or developmental anomaly in which the eyeballs are abnormally small. "(iii) Finally, here we show that the mutation of the paralogs vsx1 and vsx2.2 results in severe microphthalmia in medaka larvae." (PMID 37227126, 2023). "Gene knockdown studies have already identified that the endogenous functions of pax6a, pax6b, vsx1, otx2, and rx1 are clearly involved in the eye morphogenesis of vertebrates, and changes in the expression levels of these genes could cause various eye diseases, like microphthalmia." (PMID 38251014, 2024).
myopia (2 papers, 2024). "Surprisingly, genes associated with retinal disorders (CLUL1, VSX1, RD3, RS1, and CABP4) and a cone pigment (OPN1LW) were identified in choroid but not retina of progressing chick myopia." (PMID 39028695, 2024).
cyst (1 paper, 2023). A sac-like closed membranous structure that may be empty or contain fluid or amorphous material. "Additionally, the mRNAs for the late cyst cell markers geko and Visual system homeobox 1 (Vsx1) and the cyst cell marker eya were directly detected in spermatocytes by FISH." (PMID 36795469, 2023).
refractive error (1 paper, 2024). A defect in the focusing of light on the retina as in astigmatism, myopia, or hyperopia. "In addition, genes associated with photoreceptor function and phototransduction, such as Vsx1 and Rdh5, were changing in chick retinas and are also implicated in refractive errors in humans." (PMID 39876870, 2024).
tumor (3 papers, 2018 to 2025). "This study identified a distinct radiogenomic profile associated with VSX1 expression in ccRCC, characterized by extensive tumor necrosis, collecting system invasion, and perinephric fat stranding features commonly linked to tumor aggressiveness." (PMID 40558291, 2025). "We found that VSX1-positive tumors were more common in male patients and were associated with tumor necrosis greater than 66%, collecting system invasion, and perinephric adipose tissue stranding." (PMID 40558291, 2025). "Key features significantly associated with VSX1 positivity included male sex, tumor necrosis > 66%, collecting system invasion, and perinephric fat stranding." (PMID 40558291, 2025). "In summary, VSX1-positive expression in ccRCC has been significantly linked to specific radiological features, including extensive tumor necrosis, collecting system invasion, and perinephric fat stranding." (PMID 40558291, 2025). "In this study, we explored the clinical and radiogenomic characteristics associated with the expression of VSX1, a gene implicated in tumor aggressiveness, in patients with ccRCC." (PMID 40558291, 2025). "This study aims to investigate the computed tomography (CT) imaging features linked to VSX1 expression, hypothesizing a correlation with radiologic markers of aggressive tumor behavior." (PMID 40558291, 2025). "Their strong association with VSX1 expression further supports the hypothesis that this gene is linked to a more aggressive tumor phenotype." (PMID 40558291, 2025). "The Lasso logistic regression model identified four informative predictors of VSX1 gene expression: male sex, tumor necrosis > 66%, collecting system invasion, and perinephric fat stranding." (PMID 40558291, 2025). "It has been demonstrated that VSX1 functions as a potential oncogenic activator in ccRCC, with researchers analyzing the TCGA database to highlight its role in enhancing tumor aggressiveness in vitro." (PMID 40558291, 2025). "Conversely, compared with the empty vector control group, the overexpression of VSX1 in 786-O cells markedly enhanced tumor sphere formation ability of the cells." (PMID 36463181, 2022). "By comparing patients with positive and negative VSX1 expression, we observed that certain imaging and clinical features, such as male sex, extensive tumor necrosis, collecting system invasion, and perinephric fat stranding, were more frequent in VSX1-positive cases." (PMID 40558291, 2025). "However, VSX1 expression is also characterized by extensive tumor necrosis and perinephric fat stranding, which distinguish it from ccRCC with ADFP expression." (PMID 40558291, 2025). "In addition, the tumor sphere formation assay indicated that the ability to inhibit the tumor sphere formation in 786-O cells with the knockdown of FKBP10 after stable VSX1 overexpression was stronger than that in the shNC group." (PMID 36463181, 2022). "Collectively, these findings suggested that VSX1 acted as a tumor activator gene in ccRCC." (PMID 36463181, 2022). "However, there are limited investigations focusing on the relationship between VSX1 upregulation and tumor aggressiveness." (PMID 36463181, 2022). "Moreover, the tumor sphere formation assay revealed that knockdown of VSX1 expression in Caki-1 cells significantly inhibited the tumor sphere formation capacity of the cells compared with that of the shNC group." (PMID 36463181, 2022).
cancer (2 papers, 2013 to 2022). A tumor composed of atypical neoplastic, often pleomorphic cells that invade other tissues. "Mechanistically, high expression of VSX1 promoted cancer cell proliferation, invasion, and migration in ccRCC via transcriptional activation of downstream target genes." (PMID 36463181, 2022). "The genes—including BEST4, LMO1, ARID3C, TMEM44, FKBP10, and TRIB3—were correlated with VSX1 and might play a primary role in the transcriptional misregulation of cancer from the TCGA database." (PMID 36463181, 2022). "A recent study indicated that higher methylation frequencies in VSX1 had a significantly positive association with the risk of the high-grade non-muscle invasive bladder cancer, but the role of the VSX1 gene in other human cancers has not been confirmed." (PMID 36463181, 2022). "KEGG analysis via a bubble chart of the top 100 up- or down-regulated genes indicated that these genes showed good correlation with VSX1 and might play a leading role in the transcriptional misregulation of cancer and organic acid transmembrane transporter activity." (PMID 36463181, 2022). "Not much literature evidence has been reported for the presence of VSX1, NKX 6–2 in cancer or their methylation." (PMID 24369052, 2013).
VSX1 also shares sentences with these, for which no sentence is quoted: glaucoma (3 papers); age-related macular degeneration (1); bladder tumors (1); bradyopsia (1); cone-rod dystrophy (1); deafness (1); degenerative diseases (1); Ehlers-Danlos syndrome (1); endometriosis (1); Fuchs endothelial corneal dystrophy (1); iris hypoplasia (1); macular degeneration (1); neurologic disorders (1); retinal disorder (1); retinitis pigmentosa (1); Sotos syndrome (1); Waardenburg syndrome (1).